ANGPT1 (angiopoietin 1)
Description:
Binds and activates TEK/TIE2 receptor by inducing its dimerization and tyrosine phosphorylation. Plays an important role in the regulation of angiogenesis, endothelial cell survival, proliferation, migration, adhesion and cell spreading, reorganization of the actin cytoskeleton, but also maintenance of vascular quiescence. Required for normal angiogenesis and heart development during embryogenesis. After birth, activates or inhibits angiogenesis, depending on the context. Inhibits angiogenesis and promotes vascular stability in quiescent vessels, where endothelial cells have tight contacts. In quiescent vessels, ANGPT1 oligomers recruit TEK to cell-cell contacts, forming complexes with TEK molecules from adjoining cells, and this leads to preferential activation of phosphatidylinositol 3-kinase and the AKT1 signaling cascades. In migrating endothelial cells that lack cell-cell adhesions, ANGT1 recruits TEK to contacts with the extracellular matrix, leading to the formation of focal adhesion complexes, activation of PTK2/FAK and of the downstream kinases MAPK1/ERK2 and MAPK3/ERK1, and ultimately to the stimulation of sprouting angiogenesis. Mediates blood vessel maturation/stability. Implicated in endothelial developmental processes later and distinct from that of VEGF. Appears to play a crucial role in mediating reciprocal interactions between the endothelium and surrounding matrix and mesenchyme.
Synonyms: KIAA0003; Ang1; AGPT-1; AGP1; AGPT; HAE5
Tractability: Antibody: a drug acting on it is in phase 1 trials; UniProt places it where antibodies can reach, with high confidence; its Gene Ontology location is reachable by antibodies, with high confidence; UniProt predicts a signal peptide or a membrane-spanning region. PROTAC: ubiquitination databases record sites on it. Other modalities: a drug acting on it is in phase 2 or 3 trials.
Target class: Secreted protein
Gene: Protein-coding gene on chromosome 8 (107,249,482 to 107,498,055, reverse strand). Ensembl gene ENSG00000154188.
Subcellular location: Secreted
Pathways (Reactome):
Hemostasis: Tie2 Signaling
Signal Transduction: RAF/MAP kinase cascade
Gene Ontology:
Molecular function: identical protein binding; protein binding; receptor ligand activity; receptor tyrosine kinase binding; signaling receptor binding
Biological process: activation of transmembrane receptor protein tyrosine kinase activity; heparin proteoglycan biosynthetic process; negative regulation of apoptotic process; negative regulation of cell adhesion; negative regulation of endothelial cell apoptotic process; negative regulation of vascular endothelial growth factor signaling pathway; negative regulation of vascular permeability; positive chemotaxis; positive regulation of blood vessel endothelial cell migration; positive regulation of blood-brain barrier permeability; positive regulation of coagulation; positive regulation of endothelial cell migration; positive regulation of ERK1 and ERK2 cascade; positive regulation of gene expression; positive regulation of peptidyl-tyrosine phosphorylation; positive regulation of phosphatidylinositol 3-kinase/protein kinase B signal transduction; positive regulation of protein ubiquitination; positive regulation of receptor internalization; protein localization to cell surface; regulation of endothelial cell proliferation; regulation of skeletal muscle satellite cell proliferation; sprouting angiogenesis; Tie signaling pathway; angiogenesis; glomerulus vasculature development; and 3 more
Cellular component: extracellular exosome; extracellular region; membrane raft; microvillus; plasma membrane; extracellular matrix
Genetic constraint (gnomAD): Loss-of-function variants: 16 observed, 58.71 expected, observed/expected ratio (o/e) 0.27, 90% interval 0.18 to 0.41. The upper end of that interval is the gene's LOEUF score, 0.41, which puts it in group 1 of 6, group 1 being the genes least tolerant of losing a copy. Missense variants: 470 observed, 605.86 expected, observed/expected ratio (o/e) 0.78, 90% interval 0.72 to 0.84. Synonymous variants: 197 observed, 206.15 expected, observed/expected ratio (o/e) 0.96, 90% interval 0.85 to 1.08.
Gene-disease validity (ClinGen):
ClinGen rates the evidence that ANGPT1 causes each of these diseases.
primary congenital glaucoma (autosomal dominant): Limited.
Homologues: Orthologues: chimpanzee ANGPT1 (100% identical), macaque ANGPT1 (99% identical), dog ANGPT1 (98% identical), rat Angpt1 (98% identical), mouse Angpt1 (97% identical), pig ANGPT1 (89% identical), rabbit ANGPT1 (88% identical), guinea pig ANGPT1 (87% identical), tropical clawed frog angpt1 (82% identical), zebrafish angpt1 (67% identical). Paralogues in human: ANGPT2 (60% identical), ANGPT4 (45% identical), TNXB (30% identical), TNC (29% identical), TNR (27% identical), ANGPTL1 (27% identical), ANGPTL2 (27% identical), ANGPTL6 (26% identical), FIBCD1 (26% identical), TNN (25% identical), FN1 (24% identical), FGL2 (24% identical), and 13 more.
Diseases named in the same sentence as ANGPT1 in open-access papers:
ANGPT1 is named in the same sentence as 243 diseases in open-access papers, as found by Europe PMC text mining. Sharing a sentence is not in itself a finding about the gene and the disease. The quoted sentences say what the papers report.
Sepsis (37 papers, 2011 to 2025). Sepsis is defined as life-threatening organ dysfunction caused by a dysregulated host response to infection. "Since microvascular endothelial cells are dysfunctional during sepsis, we emphasize a separate category (E) for the genes encoding the endothelial regulatory signaling axis comprising angiopoietin-1(angpt-1) and Tie2 and others." (PMID 37638006, 2023). "The current study aims to investigate the plasma levels of angiopoietin-1 and angiopoietin-2 in patients with severe sepsis and septic shock and their association with the clinical outcome of septic shock in Vietnamese patients." (PMID 36874368, 2022). "Angiopoietin-1 and -2 are essential for embryonic and postnatal angiogenesis and stabilization and thus are associated with sepsis-induced multiple organ failure." (PMID 36874368, 2022). "The study investigated the plasma levels of angiopoietin-1 and -2 levels and their association with clinical outcomes of sepsis in plasma from 105 patients with severe sepsis by ELISA." (PMID 36874368, 2022). "The current study investigated the plasma levels of angiopoietin-1/-2 and their association with clinical outcomes of sepsis." (PMID 36874368, 2022). "The study investigated the plasma levels of angiopoietin-1/-2 and their association with clinical outcomes of sepsis in plasma from 105 patients with severe sepsis by ELISA." (PMID 36874368, 2022). "In the kidney, ALI-sepsis was associated with small increases in H3K27m3 levels at Angpt1, Tek, and Kdr, but in the liver the increase was detected at the Angpt1 gene." (PMID 25959381, 2015). "The vascular growth factor Angiopoietin-2 might also be associated with immune regulation, as it has been demonstrated that the ratio of Angiopoietin-2 to Angiopoietin-1 is associated with poor clinical outcome of early sepsis." (PMID 31057415, 2019). "Therefore, angiopoietin-1 and angiopoietin-2 have been considered useful biomarkers to improve early diagnosis, risk stratification and prognosis, especially in the early stages of sepsis progression." (PMID 36874368, 2022). "In sepsis, there is an imbalance between the angiopoietin 1 and angiopoietin 2 ratio, with a relative increase in angiopoietin 2 levels." (PMID 38406786, 2023). "Our results are consistent with the data of other authors, who revealed a high predictive value of the serum angiopoietin-1 level in relation to 28-day mortality in patients with sepsis in the ICU departments." (PMID 37238917, 2023). "The authors found that in the acute phase of sepsis, angiopoietin-1 levels are decreased compared to controls, and angiopoietin-2 levels and ratio are elevated." (PMID 37842022, 2023). "Angiopoietin-1 and -2 levels were quantified in plasma from 105 patients with severe sepsis by ELISA." (PMID 36874368, 2022). "The levels of both angiopoietin-1 and angiopoietin-2 were significantly increased in sepsis patients compared with control individuals at the time of hospital admission (T0; p = 0.0001)." (PMID 36874368, 2022). "Survivors from sepsis had higher angiopoietin-1 levels and lower angiopoietin-2 levels compared with individuals without infection." (PMID 36874368, 2022). "In conclusion, our data showed that angiopoietin-2 levels were significantly increased while angiopoietin-1 levels were decreased in patients with septic shock compared with those with severe sepsis." (PMID 36874368, 2022). "For example, circulatory Angpt1 is suppressed in patients with severe sepsis or acute respiratory distress syndrome (Giuliano Jr." (PMID 30760202, 2019). "The molar ratio of sTie2:Angpt1 found in vivo therefore is normally around 3–6 rising to 25 in severe sepsis." (PMID 28623351, 2017). "Angiopoietin-1 (Ang-1)-mediated Tie2 activation reduces, and the Ang-1 antagonist Ang-2 increases, inflammation and endothelial permeability in sepsis." (PMID 29132435, 2017).
Sepsis (continued). "There was positive correlation between ALI-sepsis-induced reduction of Pol II levels at Angpt1, Tek, and Kdr and deacetylation of H3KAc at these loci in the lung, kidney, and liver." (PMID 25959381, 2015). "Whereas Angpt1 can be protective, Angpt2 can worsen outcomes in sepsis, observations that are being used to develop biomarkers in sepsis." (PMID 25959381, 2015). "In the lungs of ALI-sepsis mice, H3KAc levels at 5′ ends of Angpt1, Tek, and Kdr were lower compared with control animals." (PMID 25959381, 2015). "After 6 hours of ALI-sepsis, Pol II levels at both the 5′ and 3′ ends of downregulated Angpt1, Tek, and Kdr genes were decreased in all three organs compared with control animals." (PMID 25959381, 2015). "Owing to these limitations, the recombinant form of human Angpt1, though effective in mice, seems inapplicable for use in patients with sepsis." (PMID 22040774, 2011). "Recombinant ANGPT1 reduces the expression of ANGPT2 induced by sepsis." (PMID 38808888, 2024). "In sepsis, angiopoietin-2 is upregulated and antagonizes angiopoietin-1." (PMID 36874368, 2022). "Similarly, biomarkers of endothelial quiescence and activation, including angiopoietin-1 (Ang-1) and angiopoietin-2 (Ang-2), have also been reported to be accurate predictors of sepsis outcome." (PMID 32605575, 2020). "Given the remaining pre-analytical technical challenges in preparing a large number of samples for epigenetic analysis, we assessed only one time point of ALI-induced sepsis and have focused on Angpt1, Tek, and Kdr, which exhibited the most pronounced mRNA downregulation." (PMID 25959381, 2015). "Sepsis is characterized by downregulation of Angpt1, Tek, Kdr, and other angiogenic genes." (PMID 25959381, 2015). "Our data suggest that transcriptionally mediated alterations in Angpt1, Tek, and Kdr during sepsis may potentially be modulated through targeting histone acetylases/deacetylases." (PMID 25959381, 2015). "The magnitude of sepsis-induced Pol II changes at all the loci matched cognate mRNA changes, suggesting that, at least in part, changes in mRNA levels reflected altered transcription of Angpt1, Tek, Kdr, and Ngal genes." (PMID 25959381, 2015). "Furthermore, treatments targeted in animal models of sepsis to block angiopoietin-2, or enhance angiopoietin-1 have been shown to be protective." (PMID 26492036, 2015). "We show that in sepsis patients, ageing was associated with a striking decrease of all measured endothelial cell activation markers (soluble E-selectin, soluble ICAM-1, fractalkine), an increase in angiopoietin-1 concentrations and a decrease of the angiopoietin-2/1 ratio." (PMID 36514130, 2022). "Thus, the down-regulation of Angpt1 in clinical conditions, such as sepsis, could be an important factor delaying recovery from AKI." (PMID 30760202, 2019). "The study also found that the angiopoietin-1/-2 ratio, angiopoietin-1/TIE-2 ratio and MEDS score were independent predictors of 28-day mortality in patients with sepsis." (PMID 36874368, 2022). "In contrast to angiopoietin-2, plasma angiopoietin-1 levels were significantly reduced in children with septic shock compared with those with critical SIRS and sepsis." (PMID 36874368, 2022). "MRNA levels of Tek receptor and its main cognate agonist/ligand, Angpt1, decreased in all three organs after 6 hours of experimental ALI-sepsis." (PMID 25959381, 2015). "Multi-analyte analysis showed elevation in proteins associated with cytotoxic lymphocytes in all IHF samples when compared to healthy controls and depression of proteins such as ANGPT1 and VEGFR2 in samples from hyperferritinemic sepsis patients relative to non-sepsis controls." (PMID 38978562, 2024). "We previously reported that elevation in endothelial biomarkers ANGPT2/ANGPT1 ratio, VCAM1, and vWF distinguished children with ARDS due to indirect (e.g., extrapulmonary sepsis or trauma, shock, transfusion, pancreatitis) compared to direct (e.g., pneumonia, aspiration, drowning) lung injury." (PMID 35913450, 2022).
Sepsis (continued). "Angiopoietin-2 and the ratio of angiopoietin-2/angiopoietin-1 were higher in hypothermic patients on day 2 compared to nonhypothermic patients with sepsis." (PMID 27737683, 2016). "Canonical Correlation Analysis with the Forward Selection and Random Forests methods identified a particular set of biomarkers that included Angiopoietin-1 (Ang-1), Angiopoietin-2 (Ang-2), and Bicarbonate (HCO) as having the strongest correlations with sepsis severity." (PMID 25255212, 2014). "Similar to our data, VEGFR2 was depressed and IL-15 elevated in a small Olink analysis of critically ill adults with sepsis (ferritin status unknown), but ANGPT1 and PDGF-subunit B levels were higher (not lower)." (PMID 39264477, 2024). "Given the absence of redundant systems to bypass the function of Angpt1/Tie2, it was speculated early that excess Angpt1 effectively abolishes microvascular leakage in experimental sepsis." (PMID 22040774, 2011). "Our results demonstrate that decreases in transcription-permissive, but not increases in transcription-repressive, histone modifications at Angpt1, Tek, and Kdr are a systemic, rather than a lung-restricted, response, involving key end-organs in experimental ALI-sepsis." (PMID 25959381, 2015).
breast carcinoma (26 papers, 2000 to 2025). "Research has shown that inhibition of ANGPT1 and its receptor, Tie2, results in human breast cancer cells becoming more sensitive to antigen-specific cytotoxic lymphocytes." (PMID 37621676, 2023). "In this study, we demonstrated that miR-153 also suppresses the migration and the tube formation of endothelial cells through directly targeting angiopoietin 1 (ANG1) in breast cancer cells." (PMID 29959560, 2018). "By crossing Angiopoietin-1 knockout mice to the MMTV-PyMT autochthonous mouse breast cancer model, we investigated primary tumor growth and metastasis to the lung." (PMID 28800750, 2017). "Taken altogether these data indicate that ANGPT1 and TGFβR2 are effectors of miR-204 and that its forced expression partially restores angiogenesis in breast cancer cells." (PMID 27703260, 2016). "The complete open reading frame of ANGPT1 and TGFβR2 genes were amplified and cloned into the pcDNA3 expression vector to overexpress the proteins in breast cancer cells." (PMID 27703260, 2016). "In addition, ANGPT1, PRG4, and RBMS3 were found to be mutated within a portion of the TCGA breast cancer samples." (PMID 37621676, 2023). "In breast cancer (BC), RNAseq revealed increased expression of transcripts encoding immune regulatory receptors (CD200R1), pro-apoptotic molecules (TNFSF10), and pro-angiogenic factors (HGF and ANGPT1) in BC patients compared to healthy donors." (PMID 36733385, 2022). "Interestingly, GTPCH1-expressing fibroblasts induced BH4-dependent breast cancer proliferation and migration by secreting angiopoietin-1 (Ang-1), which in turn triggers Tie2 phosphorylation and the activation of Ras/PI3K/AKT and ERK pathways." (PMID 34502450, 2021). "Furthermore, the expression of ANGPT1 and TGFβR2 was evaluated by Western blot in the six breast cancer cell lines which exhibits reduced miR-204 levels." (PMID 27703260, 2016). "The mRNA expression levels for eight pro-angiogenic genes [VEGFA, HGF, FGF1, FGF2, ANGPT1, ANGPT2, PDGFA, and PDGFB] were obtained from the METABRIC (Molecular Taxonomy of Breast Cancer International Consortium) dataset available at cBioPortal public domain." (PMID 39302921, 2024). "ANGPT1 and ANGPT2 belong to the angiopoietin family, which play a central role in angiogenesis and are highly expressed in a variety of tumors such as GC, breast cancer and lung cancer." (PMID 33794777, 2021). "Consistently, Angiopoietin 1 (ANGPT1) in C1, and MMPs and Endothelin 1 (EDN1) in C2 had been reported to take part in prostate or breast cancer bone metastasis." (PMID 32750747, 2020). "Recent studies showed that both ANGPT1 and TGFβR2 could be regulated by microRNAs32, however no previous involvement of miR-204 in angiogenesis in breast cancer has been described." (PMID 27703260, 2016). "This was in contrast with the expression of known HIF target genes involved in breast cancer metastasis not included in the hypoxia signatures (LOX, LOXL2, LOXL4, CCL2, L1CAM, ANGPT1, and ANGPT2), whose expression showed a positive correlation with the signatures." (PMID 29540773, 2018).